IL1B (interleukin 1 beta)
Diseases named in the same sentence as IL1B in open-access papers (continued):
Sharing a sentence is not in itself a finding about the gene and the disease.
uveitis (60 papers, 2008 to 2025). An inflammatory process affecting a part of or the entire uvea. "Interleukin-1 alpha, interleukin-1 beta, and tumor necrosis factor are shown to be associated with endotoxin-induced uveitis." (PMID 36157069, 2022). "The proinflammatory factors TNF-α, IL-1β and IL-6 are also associated with the development of uveitis." (PMID 35625654, 2022). "Activated inflammasomes, especially NLRP3, as well as the proinflammatory cytokines IL-1β and IL-18, have been implicated in uveitis." (PMID 34925047, 2021). "The levels of IL-1β in serum, tears, and AqH are increased in patients with active HLA-B27-associated uveitis and BD compared with healthy controls." (PMID 33816637, 2021). "IL-6, TNF-α, and IL-1β are also associated with dry eye, uveitis, proliferative diabetic retinopathy, and diabetic macular edema." (PMID 34285659, 2021). "IL-6 can be induced by cytokines such as IFN-γ, TNF-α and IL-1β, which is an important cytokine that causes inflammatory response of uveitis." (PMID 28384257, 2017). "The activation of Th17 cells with Th17-related proinflammatory cytokine induction (IFN-γ, TNF-α, IL-1β, IL-6, IL-23) could result in spondyloarthritis with associated uveitis." (PMID 35087531, 2021). "Research has found that PGN can significantly increase the production of IL-1β, IL-6, and IL-23 by dendritic cells (DCs) and enhance their ability to promote the generation of IL-17+ uveitis-producing T cells." (PMID 39858245, 2025). "For instance, studies using a uveitis rat model reported a significant upregulation of IL‐1β and TNF‐α gene expression in the stage of active intraocular inflammation." (PMID 36988248, 2023). "It has been shown that ANXA1 (Ac2-26) reduces the production of proinflammatory cytokines, such as TNF-α, IL-1β and IL-6, in LPS-induced uveitis." (PMID 36544058, 2023). "DC- and macrophage-derived IL-1β, TNF-α, and IL-12 have the most important pathogenic roles in the development of uveitis." (PMID 36362313, 2022). "Currently, the biologic agents targeting IL-1β mainly include anakinra, canakinumab, gevokizumab, and rilonacept, which have an efficient role in the treatment of uveitis, especially in BD." (PMID 33816637, 2021). "It was reported that macrophage-specific deletion of autophagy genes in mice leads to inflammasome-mediated IL-1β release and uveitis, which is an inflammation-mediated eye disease often observed in patients with CD." (PMID 32823867, 2020). "Gevokizumab is a recombinant humanized anti-IL-1β antibody, that modulates IL-1β bioactivity by reducing the affinity for its IL-1RI:IL-1RAcP signaling complex: it has recently been evaluated in BD patients with refractory uveitis." (PMID 25061259, 2014). "Anakinra, the IL-1 receptor antagonist, and canakinumab, the anti-IL-1β neutralization antibody, have shown improvement of retinal vasculitis lesions and uveitis flares with reduced steroid dosage in Behçet’s disease–related uveitis." (PMID 40072803, 2025). "Patients with uveitis have higher tear levels of IL-1β, a well-known immune marker of DED." (PMID 36715869, 2023). "We may summarize that the upregulation of inflammatory cytokines plays an important role in the pathophysiology of uveitis, mainly IL-6, as well as IL-1β, IL-2, INFγ, TNFα, IL-10, and GM-CSF." (PMID 33921773, 2021). "Overall, controlling the IL-1β pathway in uveitis patients deserves further exploration." (PMID 33816637, 2021). "Furthermore, when this secreted TatM013 is delivered into the retina of the endotoxin-induced uveitis mouse model, it is capable of inhibiting LPS-induced ocular inflammation and reducing the retinal concentration of interleukine-1 beta (IL-1β)." (PMID 31795515, 2019). "Consequently, multiple studies have concentrated on inhibiting IL-1β to treat uveitis." (PMID 39157460, 2024).
uveitis (continued). "Previous studies have reported that the majority of infiltrated cells within the retina after uveitis inflammation were F4/80+ macrophages, which could produce proinflammatory cytokines, such as IL-1β and TNF-α, and contribute to uveitis-associated inflammation." (PMID 37878302, 2023). "As a novel target for autoimmune uveitis, IL-6 impacts the differentiation and stimulation of Th17 cells with TGF-β and IL-23, while considering that IL-1β is necessary for the production and regulation of IL-6, the inflammasome might be highly involved in the development of uveitis." (PMID 34925047, 2021). "Therefore, several studies focused on IL-1β inhibition in the treatment of uveitis." (PMID 33171664, 2020). "d-MAPPSTM contains soluble receptors of tumor necrosis factor alpha (sTNFRI, sTNFRII) and growth-related oncogene gamma (GRO-γ), which are able to prevent IL-1β-, TNF-α-, and IL-12-driven uveitis." (PMID 36362313, 2022). "The levels of EGF, fractalkine, IL1-β, IL-17A, IL-1RA, IL-2, IL-23, IL-8, IP-10, TNF-α and IL-6 in patients with uveitis in their active phase were independent to their counterpart levels in plasma, the difference being statistically significant (p < 0.05)." (PMID 36498608, 2022). "When comparing uveitis entities, the B27+ AAU group showed significantly increased levels of IL-2, IL-6, IL-18, IL-22, IL-1β, and interferon (IFN)-γ." (PMID 34783307, 2021). "In contrast, systemic treatment with Ac2-26 reduced the IL-1β, IL-6 and GRO/KC levels, confirming its anti-inflammatory role as having been demonstrated in other experimental models of neuroinflammation and uveitis and ocular allergies." (PMID 30755225, 2019). "They found higher levels of IL-1β, IL-4, IL-17A, IL-17F, IL-21, IL-22, IL-31, IFN-γ, sCD40L, and TNF-α, with a significant difference for IL-17F, in BD-recurrent uveitis patients respect to the BD-remitted uveitis group, before drug infusion." (PMID 31134098, 2019). "Since the initial phase, the AnxA12–26 was able to reduce the expression of IL-1β, INF-γ, IL-6, TNF-α, and IL-17, corroborating studies with in vivo and in vitro models of retina autoimmune disease and uveitis in rodents and human." (PMID 30250432, 2018). "Ma and Bai found that Z-ligustilide significantly inhibited NF-κB activation and the production of IL-1β and TNF-α in experimental ovariectomized (OVX) osteopenic rats and endotoxin-induced uveitis rats." (PMID 27872860, 2016). "Production of S100B during uveitis either by resident cells in the eye or by infiltrating cells is therefore likely to have up-regulated CCL22 and IL-1β in particular resulting in further recruitment of inflammatory cells and exacerbation of disease." (PMID 26204512, 2015). "The inflammatory process leading to uveitis is mainly driven by Th17 cells and sustained by intricate sceneries directed by many proinflammatory cytokines, chiefly TNF-α and IL-1β." (PMID 25784780, 2015). "Elevated levels of IL-1β and TNF-α in the vitreous and serum of patients with uveitis suggests that uveitis is driven by a systemic inflammatory response." (PMID 22389806, 2012). "Indeed, MIA-602, but not GHRH agonist MR-409, reduced the infiltration of macrophages and leucocytes and the production of TNF-α, IL-1β and MCP-1 in a preclinical model of LPS-induced uveitis." (PMID 37649486, 2023). "Cytokines play a critical role in the pathogenesis of uveitis and we therefore investigated whether the different genotypes of rs2488457 affected production cytokines such as TNF-α, IL-1β, IL-6, IL-8, MCP-1, IFN-γ, IL-10 and IL-17." (PMID 24816862, 2014). "The effects of IL-6 in uveitis may be further augmented by ambient intraocular TNF-α and IL-1β." (PMID 34285659, 2021). "The levels of EGF, fractalkine, IL1-β, IL-17A, IL-1RA, IL-2, IL-23, IL-8, IP-10, TNF-α and IL-6 in patients with uveitis in their active phase were independent of their counterpart levels in plasma, the difference being statistically significant (p < 0.05)." (PMID 36498608, 2022).
uveitis (continued). "Comparison of classical monocytes between HC and uveitis patients revealed that common monocytic markers, e.g., CCR2, CX3CR1, HLA-DR, HLA-ABC, IL-6, IL-1β, and TNF-α were not affected (data not shown)." (PMID 30105034, 2018).
bacteremia (59 papers, 2011 to 2025). "The results showed that compared to the bacterial sepsis group, the expression of ferroptosis hub genes IL1-β and HMOX1 was decreased in the coronavirus-associated viral sepsis group." (PMID 40370730, 2025). "Excessive inflammasome activation–mediated IL-1β and IL-18 production is also reflective of monocyte/macrophage activation and has been associated with cytokine release syndromes, viral and bacterial sepsis, and autoinflammatory conditions." (PMID 33232303, 2021). "IL-17 promotes bacterial clearance in a mouse model of S aureus skin infection, IL-1β is associated with successful clearance of bacteremia in humans with SAB, and administration of IFN-γ protects against staphylococcal infections in people with chronic granulomatous disease." (PMID 40447280, 2025). "This may have been due to greater level of bacteremia experienced by the IL-1β deficient mice (WT n = 13, 2.47×108±4.36×107 CFU/mL blood; Caspase-1 KO n = 6, 7.82×108±3.18×108 CFU/mL blood; P = 0.012)." (PMID 25232870, 2014). "Therefore, inosine may have potential as a novel therapeutic tool for difficult-to-treat bacterial infections, including bacterial sepsis associated with high levels of IL-1β." (PMID 36026499, 2022). "Additionally, C. difficile damaged intestinal integrity as demonstrated by the increased serum FITC-dextran levels, causing gut leakage-induced bacteremia that enhanced the production of systemic inflammatory cytokines (serum IL-1β, TNF-α, KC, and MIP-2 levels as markers)." (PMID 34925261, 2021). "Consistently, human cathelicidin (LL-37) decreased IL-1β levels and enhanced survival in murine bacterial sepsis models." (PMID 40732710, 2025). "A significant decrease in TNFα, IL-1β, and IL-8 production was observed in patients with documented bacteremia (p value < 0.05), and a significant increase in IL-10 was also detected (p value < 0.05)." (PMID 39559359, 2024). "For instance, elevated IL-1β at the time of patient admission correlated with reduced duration of the S. aureus bacteremia." (PMID 37483624, 2023). "Low IL1β associated with HIV viremia and HIV-related complications (e.g., bacteremia, leukoplakia, neuropathy) is an exception in the literature as IL1β is considered proinflammatory and levels are typically but not always elevated in HIV." (PMID 34067023, 2021). "In contrast to bacterial sepsis, cytokines released by macrophages, such as IL-1β increase host resistance to C. albicans and alleviate disseminated C. albicans infection." (PMID 34795266, 2021). "↑mortality of mice with bacterial sepsis.↑the activation of systemic inflammasomes (such as increased IL-1β level in blood and liver)." (PMID 34163481, 2021). "The role of CNF-1 for E. coli virulence is still not clear, but a recent study demonstrated that CNF-1 activity decreases the pathogen load by potentiating LPS-triggered IL-1β-mediated antimicrobial host responses, but favors survival during bacteremia." (PMID 29390040, 2018). "It was found that the fungal sepsis is associated with substantial increase in all cytokines levels (TNF-α, IL-1β, IL-4, IL-6, and IL-10), when compared with bacterial sepsis." (PMID 28367457, 2017). "In a murine bacterial sepsis model, piperine administration sharply decreased systemic IL-1β levels, suggestive of suppression of systemic inflammation and pyroptosis." (PMID 27812336, 2016). "Piperine administration markedly reduced IL-1β levels in the peritoneal lavage fluids and serum of mice with bacterial sepsis as compared with vehicle, indicating attenuation of systemic inflammation in the circumstance of bacterial sepsis." (PMID 27812336, 2016). "As a major discovery, we demonstrated here the capacity of the host to control bacteremia through the exacerbation of LPS-driven IL-1β-mediated antimicrobial responses by CNF1 activity." (PMID 25781937, 2015).
bacteremia (continued). "While pyroptosis has a clear impact on infection, the cytokines IL-1β and IL-18 appear to play minor roles in the control of the bacteria, since IL-1β and IL-18-deficent mice show little delay in bacteremia at 72 h." (PMID 24381573, 2013). "FluA triggers a rapid activation of the innate immune pathways, such as NF-κB and STAT1/3, leading to an early and intense surge in proinflammatory cytokines, including TNF-α, IL-6, and IL-1β, that surpasses both the speed and magnitude of responses observed in bacterial sepsis." (PMID 41321454, 2025). "These investigations similarly reported suppression of IL-1β production and bacterial sepsis." (PMID 41345109, 2025). "Furthermore, in a clinical setting, lower serum levels of IL-1β were shown to be detrimental in the course of S. aureus bacteremia." (PMID 39981298, 2024). "For instance, it was recently reported that during the early stages of Staphylococcus aureus bacteremia, increased levels of IL-10 are related to persistent bacteremia and higher mortality, while increased levels of IL-1β, after three to seven days of antibiotic therapy, are related to survival." (PMID 35563218, 2022). "Thus, for bacterial sepsis where IL-1β facilitates septic shock, inhibition of GSDMD-mediated pore formation is considered an effective therapeutic strategy to prevent early shock caused by systemic hyperinflammation." (PMID 34795266, 2021). "In contrast to NLRP3 expression, the mRNA level of IL1B was higher in whole blood from patients with SAB compared with controls during the first days of bacteremia, with significant differences on days 1, 2, and 3 (p = .001, p = .004, and p = .021, respectively)." (PMID 31403210, 2019). "Thus, the improved survival of mice with bacterial sepsis was most likely due to attenuated systemic inflammation, as revealed by decreased serum IL-1β levels and reduced infiltration of inflammatory cells in the liver." (PMID 29375379, 2017). "Importantly, metformin administration increased the mortality of mice with bacterial sepsis, which was likely because metformin treatment enhanced the systemic inflammasome activation as indicated by elevated serum and hepatic IL-1β levels." (PMID 28018360, 2016). "Recently, in a bacteremia mouse model, HlyA inhibited IL-1β secretion." (PMID 27829462, 2016). "Early response cytokines (i.e. first wave at initiation of bacteremia) included IFN-γ, IL-1β, IL-6, IL-18, IL-1ra, IL-10, IL-12 (p40), IL-17a and MCP-1, which all reached peak levels during bacteremia." (PMID 35925895, 2022). "Here, we show that septic JAM-A –/– mice have increased gut permeability, yet paradoxically have decreased bacteremia and systemic TNF and IL-1β expression." (PMID 35819838, 2022). "Moreover, the mortality of bacterial sepsis mice was increased by metformin administration, which may be because metformin promoted the activation of systemic inflammasomes in mice, as shown by increased serum and liver IL-1β levels." (PMID 34163481, 2021). "Piperine, an alkaloid present in black pepper (Piper nigrum L.), protected macrophages from pyroptosis and decreased IL-1β and HMGB1 release by suppression of ATP-induced AMPK activation, suggesting the potential of piperine to be a therapeutic agent against bacterial sepsis." (PMID 36588685, 2022). "Despite no bacteremia in all groups (data not shown), serum IL-1β, IL-6, and TNF-α (but not IL-10) were increased in the infected mice from both bacterial strains." (PMID 35955437, 2022). "In addition, the mRNA expression of NLRP3, CASP1, and IL1B was altered in patients with SAB compared with healthy controls, indicating a modified priming state of the NLRP3 inflammasome during bacteremia." (PMID 31403210, 2019). "Our data indicated that piperine could protect macrophages from pyroptosis and reduced IL-1β and HMGB1 release by suppressing ATP-induced AMPK activation, suggesting that piperine may become a potential therapeutic agent against bacterial sepsis." (PMID 27812336, 2016).
bacteremia (continued). "The bacteria burdens in organs of IL-1β-treated mice 72 hours post infection were dramatically higher than the control group and bacteremia was detected in IL-1β-treated mice but not control mice." (PMID 22241982, 2011). "Bacterial sepsis induces systemic inflammation, which stimulates PCT production in almost all tissues released into the blood stream in response to bacterial endotoxins and inflammatory cytokines, such as tumor necrosis factor-alpha (TNF-α), interleukin-1-beta (IL-1β), and interleukin-6 (IL-6)." (PMID 39195007, 2024). "As IL-1β secretion in vivo upon Gram-negative bacterial infection has been shown to be NLRP3 dependent, these results suggested that scutellarin protected mice against bacterial sepsis probably by suppressing NLRP3 inflammasome activation upon microbial infection." (PMID 29375379, 2017). "We believe that differences in TNF‐α and IL‐1β plasma levels could not be detected in the COVID‐19 groups, in comparison with the healthy individuals, because the cytokine storm is milder in SARS‐CoV‐2 infections than in bacterial sepsis, being more difficult to detect." (PMID 38328863, 2024).